TNF (tumor necrosis factor)
Diseases named in the same sentence as TNF in open-access papers (continued):
Sharing a sentence is not in itself a finding about the gene and the disease.
depression (continued). "Vagus nerve stimulation has been shown to increases immune activity by elevating plasma levels of inflammatory cytokines, such as TNF-α and IL-6 in humans with depression." (PMID 32677895, 2020). "Even some polymorphisms of pro-inflammatory cytokine genes, including IL-1β, TNF, and CRP, appeared to be linked with depression and treatment response." (PMID 32517269, 2020). "TNF-α is a key cytokine involved in many neurological disorders, ranging from simple inflammation to dementia, depression, and infectious disorders." (PMID 31991572, 2020). "Previous studies have also found a decreased amount of Corynebacterium in patients suffering from depression and autism spectrum disorder, while Corynebacterium has been positively correlated with pro-inflammatory TNF-α." (PMID 33614635, 2020). "We found increases in the mean levels of CRP, IL-3, IL-6, IL-12, IL-18, sIL-2R and TNF α in patients with depression." (PMID 32113908, 2020). "Fortunately, we have found the important role of TNF-α in the inflammatory mechanism of depression-chronic somatic pain comorbidity, which lays the foundation for TNF-α regulator as a new drug target for the treatment of the disease." (PMID 33144854, 2020). "There is strong evidence that depression is accompanied by an increase of proinflammatory cytokines e.g., interleukin-1 (IL-1), IL-2, IL-6, tumor necrosis factor-α (TNFα), and acute phase proteins." (PMID 33324599, 2020). "When infused into the rat brain prefrontal cortex for 21 days in a model of depression (chronic unpredictable stress paradigm), R-BHB was shown to prevent the increase in TNF-α and the decrease in corticosterone brought about by the depression-inducing stress." (PMID 33014275, 2020). "Patients with depressive disorders have high levels of inflammatory markers and mediators, including TNF-α." (PMID 31215856, 2020). "The present findings indicate that depression is accompanied by activation of TNF-α, which also has a predictive value for the antidepressant treatment response in patients with MDD." (PMID 33364982, 2020). "Subsets of patients who suffer from depression have elevations in circulating pro-inflammatory cytokines TNF-α, IL-1β, and IL-647." (PMID 30770787, 2019). "Patients with depression exhibited an upregulation of proinflammatory cytokines, including interleukin-1β (IL-1β), IL-6, and tumor necrosis factor-α (TNF-α)." (PMID 32009949, 2019). "Clinical studies indicate that blood concentrations of the pro-inflammatory cytokine tumor necrosis factor α (TNFα) correlates with depression and impaired performance on memory tests." (PMID 30837902, 2019). "It was found that GTS treatment can alleviate depression‐like behaviour impairments and decrease mRNA levels of IL‐1b, IL‐6, TNF‐a and IDO in the hippocampus." (PMID 31599060, 2019). "The concentration of cytokines (IL-6, TNF-α, IL-17A, IL-10) was measured in the serum of healthy subjects and BD patients in remission or depression." (PMID 30971748, 2019). "Elevated levels of pro-inflammatory cytokines such as interleukin-1β (IL-1β) and tumor necrosis factor-α (TNF-α) have been observed in patients suffering from depression." (PMID 31878316, 2019). "In a chronic mild stress (CMS) model of depression, higher concentrations of IL-1β and IL-6 in the brain and IL-6 and TNF-α in serum were shown." (PMID 30610610, 2019). "Clinical studies have revealed that circulating markers of immune activation, such as increased numbers of granulocytes and monocytes and elevated levels of TNF-α and IL-6, are observed in the blood of individuals with depression." (PMID 31540304, 2019). "The picture that emerges is that depression is associated with elevations in TNF-α, and treatments aimed at reducing circulating TNF-α produce significant normalization of depressive symptoms." (PMID 30804748, 2019).
depression (continued). "The finding that FLX improved depressive behavior and pain through normalized 5-HT concentrations and TNF-α mRNA expression establishes the initial mechanism of the comorbidity of pain and depression." (PMID 31616368, 2019). "Increases in biomarker levels were correlated with reduction in depression severity for TNF-α, IL-6 IL-10 and CRP." (PMID 31375659, 2019). "We ran a reduced model including the covariates depression, anxiety, and pain alongside LT-α and TNF-α." (PMID 31250166, 2019). "Preclinical study has shown that the deletion of TNF-α is associated with antidepressant-like effects in behavioral tests in mice in comparison with wild-type mice, which further implicates TNF-α as having an important role in the development of depression." (PMID 31049023, 2019). "A few postmortem brain studies suggest that expression of innate immune responders (IL-1β, IL-6, TNF-α) and TLRs are altered in postmortem brain of suicide victims, which includes suicide subjects with major depression." (PMID 30214045, 2019). "Increases in serum pro- and anti-inflammatory cytokines have been observed in patients with depression, such as IL-1β, IL-6, and TNF-α, and IL-10, respectively." (PMID 30678337, 2019). "Excessive secretion of proinflammatory cytokines such as IL-1β, IL-6, and TNF-α triggers depression-like behavior; indeed, increased levels of such cytokines are found in the periphery and brains of patients with major depressive disorders." (PMID 31241715, 2019). "Studies have found that people with major depression have higher levels of pro-inflammatory cytokines, for example, IL-1, IL-6, and tumor necrosis factor-alpha, and C-reactive protein." (PMID 31214060, 2019). "Together, these results show that the increased anxiety-like and depression-like behavior displayed by rats with S1PR3 knock-down in the mPFC was due to elevated TNFα expression." (PMID 31316053, 2019). "LPS is an effective and potent inducer of inflammatory cytokines (eg, TNF‐α; IL‐1β; IL‐6) that can acutely activate the innate immune system in the peripheral or central nervous system to induce depression‐like behaviours." (PMID 31599060, 2019). "In a Bavarian cohort with history of depression elevated blood levels of TNFα, two isoforms of the soluble TNFα receptor and diabetes were commonly observed." (PMID 30837902, 2019). "Salidroside also significantly attenuated the levels of IL-6 and TNF-α in mice with depression-like behavior." (PMID 30705774, 2019). "A meta-analysis comprising 58 studies indicated that interleukin (IL)-6 and the acute phase reactant C-reactive protein (CRP) were elevated in major depressive disorder, and to a lesser extent, tumor necrosis factor (TNF)-α." (PMID 30967802, 2019). "The serum levels of proinflammatory cytokines such as interleukin 6 (IL-6), tumor necrosis factor α (TNF-α), and IL-1β are elevated in major depressive disorders." (PMID 30705774, 2019). "Significantly higher TNFα and lower IL-10 levels have been shown in depressed SLE patients and have been associated with worse depression scores." (PMID 31379879, 2019). "In particular, tumor necrosis factor-α (TNF-α), interleukin-1β (IL-1β), and IL-6 are increased during depression, as well as associated with cognitive impairment." (PMID 31611786, 2019). "Increasing evidence points to a pro-inflammatory state in patients with unipolar depression (increased serum interleukin (IL)-6) and bipolar depression (increased levels of IL-1, IL-6 and TNF-alpha)." (PMID 31671812, 2019). "In a recent clinical study, the role of TNF-α in the development of depression and anxiety in a systemic inflammatory disease, systemic lupus erythematosus (SLE), was explored." (PMID 31049023, 2019). "Pro-inflammatory cytokines, such as interleukin (IL)-6 and tumor necrosis factor-α (TNF-α), are thought to play a fundamental role in the pathogenesis of depression within a subset of individuals." (PMID 30967802, 2019).
depression (continued). "Some authors have reported a correlation between higher levels of IL-6 and TNF-α and depression scores (CES-D) in subjects displaying major depression, but not with high scores for stress perception in Afro-American and Caucasian pregnant women." (PMID 30943938, 2019). "Treatment with proinflammatory cytokines, including IL-1, IL-6, or TNF-α, or lipopolysaccharide (LPS), induces sickness behavior and corresponding depression-like behavior on the forced swim test." (PMID 30804748, 2019). "Patients with depression frequently exhibit increased levels of C-reactive protein, tumor necrosis factor-alpha, and interleukin-6 (Miller, Maletic & Raison, 2009)." (PMID 31592197, 2019). "The data from a clinical study suggest that plasma tumor necrosis factor (TNF)-α is also correlated with depression severity, and anti-TNF-α treatment alleviates depressive mood." (PMID 31275120, 2019). "The reserpine-induced rat depression model significantly elevated the expression levels of IL-1β, IL-6, and TNF-α in the serum, liver and hippocampus of rats compared with the control group (P < 0.01 or P < 0.05)." (PMID 32009949, 2019). "In our study, the levels of IL-1β, IL-6, and TNF-α were substantially increased in the hippocampus of the depression mice model induced by CUMS." (PMID 31068207, 2019). "The three anti-TNF-a drugs and the anti-IL-6 antibody (tocilizumab) significantly improved symptoms of depression." (PMID 31214060, 2019). "Secretion of more proinflammatory cytokines [such as interleukin 6 (IL-6) and tumor necrosis factor alpha (TNF-α)] are reported in both patients with depression and animal models of depression." (PMID 31798446, 2019). "Another independent study in major depression also showed that LPS-induced monocytes from patients with depression secreted lower levels of IL-1β, IL-6, and TNFα than those from the control group." (PMID 31152269, 2019). "This review outlines the immunological mechanism of T1D and depression, with a particular emphasis on the role of tumor necrosis factor-α (TNF-α), IL-1β, and interferon-γ (IFN-γ) cytokines and their signaling pathways." (PMID 31049023, 2019). "In the present study, the LPS-induced depression model produced the proinflammatory cytokines (IL-6 and TNF-α), and IL-6 positive cells were identified primarily in the dentate gyrus (DG) of rats." (PMID 31798446, 2019). "For example, inflammatory proteins, such as C-reactive protein (CRP), and cytokines, such as interleukin (IL)-6 and tumor necrosis factor (TNF)-α, have been elevated in people with depression." (PMID 30987242, 2019). "In a model of major depressive disorder, TNF-α expression is increased, and an antidepressant treatment decreases the expression of ADAM17 and its targets CXCL2 and IL-6." (PMID 30586315, 2019). "At the same time, patients in remission were characterized by decreased TNF concentration compared with healthy people and patients in depression." (PMID 30971748, 2019). "Considerable work has demonstrated that circulating inflammatory markers (e.g., IL-1β, TNF, IL-6, and C-reactive protein) are important covariates for depression and anxiety in humans." (PMID 32047493, 2019). "In a more recent, larger scale meta-analysis a greater range of changes have been described in people with depression, including higher levels of TNFα, IL-6, IL-13, IL-18, IL-12, IL-1RA, and sTNFR2, along with a decrease in the proinflammatory cytokine IFNγ." (PMID 31379879, 2019). "Animal experiments have shown that cytokine blockers like TNF-α blockers can be effective in the treatment of depression-like behavior." (PMID 30792669, 2019). "Animal models of depressive disorders have shown an increase in pro-inflammatory markers, such as interleukin-6 (IL-6), interleukin-1β (IL-1β) and tumor necrosis factor alpha (TNF-α)." (PMID 30678337, 2019).
depression (continued). "Depressive disorder was found to link with an increase in expression of various central and peripheral proinflammatory cytokines, including tumor necrosis factor α (TNF-α) and interleukin-1, interleukin-6 (IL-1, IL-6), and interferon- α and γ." (PMID 31881712, 2019). "Depression derives from activation of immune-inflammatory pathways, according to that the release of IL-1β and TNF-α triggers off neuroendocrine and neurochemical deterioration." (PMID 30364169, 2018). "Correspondingly, a recent study by Mrugacz and colleagues revealed that the tear fluid levels of interleukin (IL)-6, IL-17 and tumor necrosis factor (TNF)-α were significantly higher in patients with depression than in controls." (PMID 30096194, 2018). "Peripheral inflammatory response can lead to depression, the inflammatory factors (IL-6, TNF-α and CRP) are mainly synthesized by monocytes and produce inflammatory response and promote immune response." (PMID 30181997, 2018). "We found linear correlations between IL-1β, TNF-α, and IL-8, and the severity of depression, as well as between IL-8 and anxiety level in patients with comorbid anxiety disorder (p < 0.05)." (PMID 29856741, 2018). "IL-6 and TNF-α alter the metabolism of norepinephrine, serotonin, and dopamine and lead to symptoms of depression." (PMID 29619128, 2018). "The UPR acts on proinflammatory cytokines such as IL-8, IL-1β, and TNF-α, and these cytokines have been found to be upregulated in patients with major depression." (PMID 30186550, 2018). "Among many other mechanisms, synaptic scaling is regulated by inflammatory cytokines (e.g., tumor necrosis factor) and by neurotrophins [e.g., brain-derived neurotrophic factor (BDNF)], alteration in both factors has been associated with depression." (PMID 30197765, 2018). "The degradation of serotonergic neurons induced by LPS in the fetus is attributed to the increased levels of interleukin (IL)-6 and tumor necrosis factor (TNFα) as well as to anxiety and depression in children." (PMID 30469423, 2018). "A single dose of TNF-α by ICV injection induced anxiety- and depression-like behaviors, while antagonizing TNF-α abolished those behaviors." (PMID 30208926, 2018). "In these strata, we found a difference in levels of IL-1RA in the minimal to mild depression group, and in levels of IL-1RA and TNF-α in the severe depression group." (PMID 29631540, 2018). "For example, persons with depression exhibit a decrease in the pro-inflammatory cytokine TNF-α after submax exercise along with an increase in anti-inflammatory IL-4." (PMID 30093853, 2018). "A meta-analysis indicated that the inflammatory markers associated with depression are TNFα, IL-1, IL-6 and CRP and there are many reports showing the association between serum IL-6 increase and depression." (PMID 30423923, 2018). "Compared to IL-6, reports indicated that the relationships between depression and TNF-α, IL-12 and IL-10 are few." (PMID 30400354, 2018). "Strikingly, systemic IL-1B and TNFα were significantly elevated and positively correlated with patient anxiety and depression scores in a large clinical study on CP/CPPS patients." (PMID 29731970, 2018). "This was also true for levels of TNF-α with the same strata in the severe depression group (p = 0.029)." (PMID 29631540, 2018). "This suggests that depression alone can independently predict flare in patients who taper their anti-TNF agents." (PMID 29862047, 2018). "Clinical studies report higher levels of circulating proinflammatory cytokines, such as interleukin-1β, interleukin-6 (IL-6), and tumor necrosis factor-α (TNF-α), in patients with major depressive disorder (MDD)." (PMID 29861834, 2018). "Microglia release pro-inflammation mediators, such as IL-6, IL-1β, TNF-a, and nitric oxide that are considered links between chronic pain and depression." (PMID 30356873, 2018).
depression (continued). "This evidence supports the direct or indirect participation of TNF-α in the development of depression, which gives meaning to our finding of high levels of TNF-α in MDD adolescents." (PMID 30662368, 2018). "More importantly, studies have clearly shown that NF-κB increased IL-1β and TNF-α expression in the hippocampus and frontal cortex during stress and regulated neurogenesis in the hippocampus which were closely related with depression." (PMID 29765402, 2018). "A trial with add-on infliximab (an inhibitor of the inflammatory TNF-alpha) has revealed an increased clinical response compared with antidepressants alone in patients with treatment-resistant depression, but only in those with a CRP of >5 mg/L." (PMID 29615964, 2018). "Inflammatory cytokines, such as interleukin (IL)-6, IL-1β, IL-8, and tumor necrosis factor (TNF)-α as well as the transcription factor NF-κB, function in the pathogenesis and development of chronic pain and depression." (PMID 30356873, 2018). "In contrast, targeting TNFα would be more appealing in light of its role in the pathophysiology of depression, particularly deficits in serotonin neurotransmission." (PMID 29941989, 2018). "Further research is needed to examine the moderating and mediating effects of BMI on depression with additional biomarkers, e.g., malondialdehyde, F2-isoprostanes, 8-hydroxy 2′-deoxyguanosine, neuropeptide Y, adiponectin, IL-6, TNF-α, and IL-17." (PMID 30524737, 2018). "In two studies of infliximab which blocks tumor necrosis factor (TNF)-α in patients with major depression, treatment only benefited participants with CRP above a certain level." (PMID 30766494, 2018). "LPS transiently increased interleukin-6 and tumor necrosis factor-α, sickness symptoms, body temperature and self-reported fatigue, and depression post injection relative to baseline and placebo." (PMID 28948979, 2018). "Whereas none of the other mediators showed a differential association with depression by HIV status, the association between abuse and TNF-α (p<0.01), IL-1α (p<0.01) and IP-10 (p<0.01) was significantly lower in HIV infected compared to uninfected women." (PMID 29894487, 2018). "As IL-1β, IFN-α/γ, TNF-α, and IL-6 have also been related to the onset and development of depression." (PMID 30662368, 2018). "The proinflammatory cytokines IL-1, IL-6, and TNF-α are thought to play a primal role in the neurotransmitter and neuroendocrine changes that occur in depression given their central role in sickness behavior." (PMID 30093853, 2018). "We found linear correlations between IL-1β, TNF-α, and IL-8, and the severity of depression, as well as between IL-8 and anxiety level in patients with comorbid anxiety disorder." (PMID 29856741, 2018). "Several clinical trials using monoclonal anti-TNF-α antibodies (etanercept and infliximab), which block the inflammatory activity of TNF-α, have shown the influence of TNF-α in depression." (PMID 30662368, 2018). "Recently, a proof-of-concept randomised controlled trial (RCT) of infliximab, an anti-TNF monoclonal antibody, has reported improvements in patients with treatment resistant depression characterized by high inflammation at baseline." (PMID 29197507, 2018). "We also investigated the effect of CVS on the concentration of major cytokines associated with depression, i.e., IL-1β, IL6, and TNF-α in the blood of rats." (PMID 30533439, 2018). "The results of a meta-analysis of 24 studies measuring cytokines in depressed patients, found that individuals with Major Depression had significantly higher concentrations of Tumoral Necrosis Factor alpha (TNF-α) and Interleukin 6 (IL-6) compared to controls." (PMID 30108549, 2018). "Higher levels of IL-1β, IL-6, and TNF-α in the brain were believed to induce depression due to DAMPs under stress." (PMID 29765402, 2018).